KANK1 (KN motif and ankyrin repeat domains 1)
Diseases named in the same sentence as KANK1 in open-access papers (continued):
Sharing a sentence is not in itself a finding about the gene and the disease.
myeloproliferative neoplasm (2 papers, 2017 to 2023). A clonal hematopoietic stem cell disorder, characterized by proliferation in the bone marrow of one or more of the myeloid (i.e., granulocytic, erythroid, megakaryocytic, and mast cell) lineages. "KANK1 mutations were also associated with myeloproliferative neoplasm, and a fusion protein of KANK1 with PDGFRB was found as an oncogene due to a t(5:9) translocation." (PMID 28067315, 2017).
oral squamous cell carcinoma (2 papers, 2021 to 2022). "Moreover, KANK1 has been shown to regulate Yap expression, inhibiting cell proliferation and inducing apoptosis in oral squamous cell carcinoma cells." (PMID 34349117, 2021).
carcinoma in situ (1 paper, 2024). "KANK1-KOPyMT mice developed fewer numbers of small foci of carcinoma in situ scattered throughout the otherwise normal mammary gland at the time of initial tumor palpation." (PMID 39613731, 2024).
Cirrhosis (1 paper, 2024). A chronic disorder of the liver in which liver tissue becomes scarred and is partially replaced by regenerative nodules and fibrotic tissue resulting in loss of liver function. "In conclusion, this study revealed the expression profile of eccDNA in HBV-related liver cancer and cirrhosis, ultimately identifying the target genes LAMA4[circle112550019-112550510] and KANK1[circle674459-674907]." (PMID 39850493, 2024).
coronary artery disease (1 paper, 2023). "The significant SNP identified within KANK1, rs2296055 (chr9:676,954:T > C), was previously identified in a study considering variants associated with coronary artery disease in an Indian population of 153 individuals." (PMID 37731134, 2023).
Cri-du-chat syndrome (1 paper, 2021). Monosomy 5p, also known as Cri du chat syndrome, is a rare autosomal deletion syndrome characterized by a mewing cry (cri du chat) in infancy, multiple congenital anomalies, intellectual disability, microcephaly, and facial dysmorphism. "For fetus 20, SNP array analysis revealed a 32 Mb deletion at 5p15.33p13.3 (involving CTNND2 and DOCK8) which caused cri-du-chat syndrome, and a 21 Mb duplication at 9p24.3p21.3 (involving KANK1) leading to 9p duplication syndrome." (PMID 33674646, 2021).
diabetes (1 paper, 2023). "An unclassified form of diabetes caused by mutation in the KANK1 gene was identified in P5." (PMID 38162681, 2023).
ependymoma (1 paper, 2022). A WHO grade II, slow growing tumor of children and young adults, usually located intraventricularly. "Pathologists reported two cases (KANK1:NTRK2 and RAF1:QKI) as ependymomas, but these tumors were reclassified as low-grade glioma due to the clinical course, underlying molecular alteration, and methylation profile." (PMID 36163281, 2022).
fibroid (1 paper, 2024). "For example, while KANK1 is substantially upregulated predominantly in SMCs, VCAN is highly expressed selectively in fibroblasts in fibroid tumors." (PMID 38326302, 2024).
kidney cancer (1 paper, 2022). Primary or metastatic malignant neoplasm involving the kidney. "The Kank1 gene was first identified to act as a tumor suppressor in kidney cancer, and the induction of Kank1 has been found to inhibit cell proliferation and promote the mitochondrial apoptotic signaling cascade." (PMID 35805114, 2022).
liver cancer (1 paper, 2024). An epithelial or non-epithelial malignant neoplasm that arises from the liver. "Experiments have verified that LAMA4[circle112550019-112550510] and KANK1[circle674459-674907] are real and expressed target genes, and their source genes are closely related to the survival time of patients with liver cancer." (PMID 39850493, 2024).
Macrocephaly (1 paper, 2021). Occipitofrontal (head) circumference greater than 97th centile compared to appropriate, age matched, sex-matched normal standards. "Here we report findings of duplications of chromosome location 9p24.3 (i.e., the DOCK8/KANK1 genes) in three unrelated patients, which provide evidence of the pathogenic impact of this duplication in patients with ID/DD, ASD, ADHD, and macrocephaly." (PMID 33455084, 2021). "Additionally, mosaic duplication involving the DOCK8, DMRT1, DMRT2, DMRT3, and KANK1 genes were observed in patient 2, which may explain the presence of macrocephaly in this patient." (PMID 33455084, 2021). "In this study, only patient 2 had macrocephaly and his duplication overlapped the DOCK8 and KANK1 genes, unlike the remaining patients who carried an intragenic duplication of DOCK8 only." (PMID 33455084, 2021).
metanephric adenoma (1 paper, 2023). A benign, well-circumscribed renal cortical neoplasm affecting females more often than males. "Moreover, KANK1 has been discovered to fuse with neurotrophic receptor tyrosine kinase 3 (NTRK3) gene in patient samples with pathologically confirmed metanephric adenoma leading to a subset of B-Raf proto-oncogene, serine/threonine kinase (BRAF) mutations." (PMID 37731134, 2023).
neurofibroma (1 paper, 2017). An intraneural or extraneural neoplasm arising from nerve tissues and neural sheaths. "Consistently, knockdown of KANK1 in neurofibroma cells promoted cell growth." (PMID 28067315, 2017).
neurosyphilis (1 paper, 2021). Infection of the brain or spinal cord by Treponema pallidum. "Taken together, our findings suggest a novel mechanism that LncRNA-ENST00000421645 upregulates Kank1 to inhibit IFN-γ expression and promote T cell apoptosis in neurosyphilis." (PMID 34917045, 2021).
pancreatic ductal adenocarcinoma (1 paper, 2021). An infiltrating adenocarcinoma that arises from the epithelial cells of the pancreas. "In this case, we first reported targeted comutation of somatic novel KANK1-ALK, UPP2 intergenic NTRK3 fusion, and pathogenetic germline BRCA1 mutation in a pancreatic ductal adenocarcinoma patient." (PMID 34671564, 2021). "Herein, we firstly presented a case about pancreatic ductal adenocarcinoma patient concurrent to targetable rare somatic novel KANK1-ALK, UPP2-NTRK3 fusion, and pathogenetic germline BRCA mutation." (PMID 34671564, 2021). "Based on next-generation sequencing (NGS), we firstly presented a case about a KRAS wild-type pancreatic ductal adenocarcinoma patient harboring a concurrent targetable rare somatic novel KANK1-ALK, UPP2-NTRK3 fusion, and pathogenetic germline BRCA mutation." (PMID 34671564, 2021).
renal carcinoma (1 paper, 2026). A carcinoma arising from the epithelium of the renal parenchyma or the renal pelvis. "The majority of the ACA variants were found to co-occurred in ACC (n = 36/42) and were benign, except for two of unknown significance in KANK1 and REN genes, described as associated with renal cancer." (PMID 41806143, 2026).
Stroke (1 paper, 2016). Sudden impairment of blood flow to a part of the brain due to occlusion or rupture of an artery to the brain. "The targetgenes of miR-181b, such as DDIT4 and Kank1, were also found to be related to stroke." (PMID 26830013, 2016).
Ventriculomegaly (1 paper, 2023). An increase in size of the ventricular system of the brain. "Hypothetically, ventriculomegaly may be act as a common ancestor phenotype between KANK1 and enlarged sylvian cistern." (PMID 36691971, 2023).
tumor (24 papers, 2011 to 2025). "To decipher the mechanism of KANK1’s role in tumor development in vivo, we generated the Kank1-floxed allele in mice." (PMID 39613731, 2024). "The KANK1 gene is methylated in the kidneys, lungs, and brain tissues, and low KANK1 levels have been associated with tumor progression in various cancer types." (PMID 34349117, 2021). "Smaller tumour size and negative association with TGFB1, CDH2 and LLGL2 strengthen the tumour suppressive role of KANK1." (PMID 31679074, 2020). "High KANK1 protein expression was associated with smaller tumour size (p = 0.012) and HER2 positivity (p = 0.007)." (PMID 31679074, 2020). "To identify the cell(s) that express KANK1 in KANK1-WTPyMT tumors, we immunostained tumor sections and observed high KANK1 levels exclusively in KANK1-WTPyMT LECs." (PMID 39613731, 2024). "At the 21-week timepoint, most of the KANK1-WTPyMT tumors reached the volume and weight approved by the ethical committee, whereas the KANK1-KOPyMT tumor weights were comparable to those of the KANK1-WTPyMT tumors measured at the 16-week time point." (PMID 39613731, 2024). "At this tumor stage, KANK1 expression switches from a predominant localization at integrin adhesion sites to cell-cell junctions." (PMID 39613731, 2024). "At the 16-week time the KANK1-WTPyMT tumor burden was three-fold higher and the tumor size significantly larger compared to KANK1-KOPyMT tumors." (PMID 39613731, 2024). "In the present study, we find that KANK1 promotes tumor growth by changing the subcellular location from integrin adhesions to cell-cell junctions, where KANK1 competes with SCRIB for the binding to NOS1AP." (PMID 39613731, 2024). "The accelerated tumor development in KANK1-WTPyMT mice was due to an elevated tumor cell proliferation and survival." (PMID 39613731, 2024). "Over the last five years, accumulating evidence has confirmed that Kank1 plays a tumor-suppressive role in many malignancies." (PMID 35805114, 2022). "KANK1 has also been reported to exert a tumor-suppressive effect by regulating the Wnt/β-catenin/Axin2 pathway in GC development." (PMID 35320976, 2022). "KANK1 was among the first found to be downregulated in a variety of tumors and has been identified as a tumor suppressor." (PMID 35559038, 2022). "Among genes upregulated in this group, CBX7, MIA3 and KANK1 have been shown to have tumor suppressive activities including roles in inhibition of cellular motility/migration and/or proliferation, and induction of cell cycle arrest in various malignancies." (PMID 32310997, 2020). "KANK1 appears to play a role in inhibiting tumour cells proliferation, migration, invasion and metastasis." (PMID 31679074, 2020). "Using the median H-score as a cut-off point, high KANK1 expression was observed in 599/1500 (40%) of tumours." (PMID 31679074, 2020). "Further functional studies to decipher the role of KANK1 and its mechanism of action as a tumour suppressive driver of invasive BC is warranted." (PMID 31679074, 2020). "Additional animal models of KANK1 are needed for further evaluating in vivo tumor suppressor functions of KANK1." (PMID 28067315, 2017). "By the end of week six, tumor volumes in the doxycycline-induced KANK1 expressing mouse group were significantly smaller." (PMID 28067315, 2017). "We have already created a few loss-of-function zebrafish kank1a and kank1b mutants using CRISPR, and are currently investigating KANK1’s tumor suppressor capacity." (PMID 28067315, 2017). "In tumor sections, Kank1 was stained in papillary RCC and ACD-RCC and weakly or negatively in all other tumors." (PMID 24995295, 2014). "Human Kank1 was identified as a tumour suppressor and has documented roles in actin regulation and cell polarity in cultured mammalian cells." (PMID 25203404, 2014). "The gene for Kank1 (Kank1) was found to be a tumor suppressor gene and its expression was decreased or lost in renal tumors." (PMID 24995295, 2014).
tumor (continued). "Kank1 was found as a tumor suppressor of clear cell RCC, and the locus (9p24.3) is frequently deleted in clear cell RCC." (PMID 24995295, 2014). "The parent gene, KANK1, exerts its anti-tumor effect by promoting tumor cell apoptosis." (PMID 39850493, 2024). "In search for a mechanistic explanation for the increased tumor growth in KANK1-WTPyMT mice, we discovered several steps of an oncogenic signaling pathway, in which KANK1 undertakes the principal task to impair the tumor suppressive function of the cell polarity protein SCRIB." (PMID 39613731, 2024). "The aggravated tumor formation in KANK1-WTPyMT mice could result from increased proliferation and/or survival of transformed LECs." (PMID 39613731, 2024). "The KANK1-WTPyMT tumoroids grew faster compared to KANK1-KOPyMT tumoroids and contained significantly more Ki67+ cells at the experimental end point, which confirms our hypothesis that KANK1 promotes tumor growth in a cell-autonomous manner." (PMID 39613731, 2024). "As expected, overexpression of KANK1 significantly inhibited GC tumor growth and metastasis." (PMID 35320976, 2022). "KANK1 has been reported to participate in tumorigenesis and tumor progression in various cancers." (PMID 35320976, 2022). "As TRAIP acts as an E3 ubiquitin ligase and KANK1 has been identified as a tumor suppressor, we evaluated whether KANK1 was a substrate of TRAIP." (PMID 34349117, 2021). "KANK1 overexpression has been correlated with restrained tumor invasion and growth in lung and gastric cancer, while its overexpression in glioma seems to lead to curbed tumor growth via enhancing apoptosis." (PMID 32878117, 2020). "Our results suggest that KANK1 may function as a tumor suppressor in human MPNSTs, and thus it may be useful for targeted therapy." (PMID 28067315, 2017). "The conserved protein Kank1 was identified as a human tumour suppressor, though exactly how it suppreses tumour growth remains unclear." (PMID 25203404, 2014). "Upon progression, a second partial resection was followed by DNA methylation profiling, which reclassified the tumor as a glioneuronal tumor with ATRX alteration, kinase fusion, and anaplastic features (GTAKA), harboring a KANK1::NTRK2 fusion." (PMID 41397922, 2025). "If NOS1AP supports the tumor suppressor function of SCRIB, depletion of NOS1AP in MCF7 KANK1-KO cells should foil the effect of KANK1 on SCRIB-mediated TAZ stability regulation." (PMID 39613731, 2024). "Immunostaining of KANK1-WTPyMT tumor sections revealed that KANK1 localized at cell-cell junction and TAZ in the nucleus (asterisks), except the tumor cells that were still attached to the BM." (PMID 39613731, 2024). "The KANK1-induced disruption of the SCRIB/NOS1AP complex curbs TAZ inhibition, resulting in increased mouse tumor cell growth in vivo, in tumoroids and in xenografted human cancer cells." (PMID 39613731, 2024). "Our study also showed that high KANK1 mRNA expression showed improved survival time in the aggressive and clinically relevant subgroups of BC, namely ER, PR and HER2-negative tumours." (PMID 31679074, 2020). "When we stratified our BC cohort based on hormonal receptor and HER2 expression, overexpression of KANK1 protein was predictive of longer BCSS in the receptor-negative subgroups (p = 0.024, p = 0.038 and p = 0.014 for ER−, PR− and HER2− tumours, respectively)." (PMID 31679074, 2020). "Overall, our experimental results provide evidence for KANK1 as a tumor suppressor in human MPNST cells, and elucidate a new mechanism of KANK1 cell growth suppression." (PMID 28067315, 2017). "Recently, we found that liprin-β1 interacts with KANK1, one of the four members of the KANK family of proteins, which were proposed to act as tumor suppressors and regulators of cell polarity and migration through Rho GTPase signaling." (PMID 27410476, 2016). "In contrast, KANK1-KOPyMT tumors showed TAZ primarily cytoplasmic, irrespective whether tumor cells were attached to or away from BM." (PMID 39613731, 2024).
tumor (continued). "Those patients with tumours showing high KANK1 protein expression had significantly better 10 years BCSS (p = 0.024) and longer TTDM (p = 0.048) compared with those patients showing low/reduced KANK1 expression." (PMID 31679074, 2020). "Multivariate analyses indicated that high KANK1 expression is correlated (< 0.05) with better outcome in terms of longer BCSS and TTDM, independent of other established prognostic variables including tumour size, Nottingham grade, nodal stage, LVI, ER status, PR status and HER2 status." (PMID 31679074, 2020). "Since KANK1 was only expressed in PyMT-transformed tumor cells and absent in myoepithelial cells and tumor stromal cells including fibroblasts, endothelial cells and infiltrating immune cells, we concluded that the tumor growth promoting effect of KANK1 is likely cell autonomous." (PMID 39613731, 2024). "Non-BRAF alterations were detected in four tumor samples consisting of CLIP2:NTRK2, KANK1:NTRK2, RAF1:QKI, and KRAS Q61H." (PMID 36163281, 2022).